TNF (tumor necrosis factor)
Diseases named in the same sentence as TNF in open-access papers (continued):
Sharing a sentence is not in itself a finding about the gene and the disease.
tumor (continued). "After rechallenge, concentrations of both TNF-α and IFN-γ in mouse sera were significantly increased, suggesting that combinational therapy could boost a strong immune memory effect to prevent the recurrence of tumor." (PMID 30406152, 2018). "In addition, inflammatory cells such as CD113b expressing myeloid cells and macrophages were also recruited leading to the formation pre-metastatic niche through increased expression of S100 calcium binding proteins following induction by TNFα, TGFβ and VEGFA secreted by primary tumour cells." (PMID 29506506, 2018). "The TNF-α/TNFR1 signaling could promote GC occurrence by inducing NADPH oxidase organizer 1 (Noxo1) and G protein subunit alpha 14 (GNA14), which are crucial in the tumorigenicity and stemness of GC cells, in tumor cells." (PMID 29867530, 2018). "It is supposed that the 5A/6A polymorphism may be associated with the MMP3 gene promoter activity under interleukin and tumor necrosis factor α (TNF α) stimulation and it may influence the transcription of the gene through the regulation by cytokines released by tumor cells." (PMID 30381735, 2018). "Lung tissues with tumor metastasis provided evidence of increased oxidative stress, as assessed by p22phox and SOD mRNA levels and the NRF2 protein level, as well as increased inflammation, as assessed by TNF-α and IL-6 mRNA levels and the NF-κB P65 protein level." (PMID 29433520, 2018). "Furthermore, when activated human T cells were co-cultured with PD-L1 positive human tumor cells, PD1-Fc- OX40L was observed to concentrate within the immune synapse, which enhanced proliferation of T cells and production of IL-2, IFNγ and TNFα; leading to efficient killing of tumor cells." (PMID 30400822, 2018). "Third, none of the articles provide information related to TNF expression levels classified by gender or stage of the tumor and therefore, we could not analyze these factors." (PMID 30413607, 2018). "In the present study, APG-1387 enhanced the cytotoxic effects of TNF-α and TRAIL on HepG2 and HCCLM3 cells to some extent, but the combination of APG-1387 with TNF-α or TRAIL resulted in a strong inhibitory effect on clonogenic survival, demonstrating long-term anti-tumor activity." (PMID 30459627, 2018). "A large amount of cytokines secreted by the TME and tumor cells are involved in this process, including interleukin (IL)-6, transforming growth factor (TGF)-β, stromal-derived factor (SDF)-1, tumor necrosis factor (TNF)-α, interferon (IFN)-γ, macrophage inhibition factor (MIF), and IL-1α." (PMID 29386041, 2018). "Furthermore, Tumor Necrosis Factor Alfa (TNF-α) activates MSCs to secrete chemokine (C-C motif) ligand 5 (CCL5), C-C chemokine receptor type 2 (CCR2), and the interleukin 8 receptor, beta (CXCR2) ligands that in turn recruit CXCR2+ neutrophils into the tumor." (PMID 28473858, 2017). "TNF-α was originally identified as a mediator of tumor necrosis in the serum of animals treated with lipopolysaccharide, and is produced by immune cells, non-immune and tumor cells." (PMID 29202842, 2017). "ELISA analysis of tumour homogenates demonstrated significantly higher TNFα levels within tumours of MG-TNFα treated mice compared with controls (mice i.v. administered engineered MG1655 lacking the TNFα gene or PBS)." (PMID 28662099, 2017). "However, tumor cells lacking SM-induced autocrine TNF release survive and thus limit therapeutic efficacy." (PMID 28771230, 2017). "However, the level of TNF-α mRNA, which may be critical for the induction of apoptosis in Her2/CT26 cells in vivo, was significantly increased in tumor tissues of TSA-treated mice compared to vehicle-treated mice." (PMID 28489607, 2017). "In most cases, TNFα acts as a promoter rather than a killer in tumor cells and tissues." (PMID 28599664, 2017). "In addition, elevation of circulating TNFα and IL-6 in LLC tumor-bearing mice is dependent on TLR4." (PMID 28536426, 2017).
tumor (continued). "However, our work revealed a new mechanism for tumour-secreted IL-6 and IL-8, but not common inflammatory cytokines such as TNFα and IL-1β secreted by immune cells, to promote tumour cell migration and metastasis." (PMID 28548090, 2017). "In mouse models of breast cancer, macrophages contribute to tumor progression through a variety of mechanisms including IL-10 and arginase 1 (Arg1)-mediated immunosuppression, MMP 7/9 and CCL18-induced matrix remodeling, and EGF and TNFα-stimulated tumor cell migration and metastasis." (PMID 28881599, 2017). "The combined treatment of TNF-α and IL-6 could induce morphological changes in A549 cells, characterized by fibroblast-like cells, while AFG1 did not cause EMT in the tumor cells." (PMID 28801561, 2017). "Tumor-associated PD-L1 expression, which may be intrinsically upregulated by activation of tumorigenic pathways or induced by acute (TNF-α and IFN-γ) or continuous/repeated stimuli (chronic inflammation), could inhibit the host immune responses and promote tumor progression." (PMID 28465490, 2017). "TNFα was identified in 1975 when it was discovered that a substance from the sera of animals that were challenged with BCG and endotoxin could kill mouse cells in vitro and induce haemorrhagic necrosis of transplantable mouse tumours in vivo." (PMID 28662099, 2017). "Thus, we concluded that IFNγ, TNFα, and IL-10 did not alter the expression of B7x in human and murine tumor cell lines." (PMID 29137299, 2017). "In docetaxel-resistant MCF-7 and A2780 cell lines, the production of TNF-α could not be significantly augmented by docetaxel without the inhibition of P-gp, a transporter protein that promotes drug efflux from tumor cells." (PMID 28915246, 2017). "Similar to TNF-α, IL-β from macrophages could also induce phosphorylation of GSK3β, stabilize β-CATENIN, and thereby increase the expression of Wnt pathway downstream target genes in tumor cells." (PMID 28402277, 2017). "Thus, we assessed whether increases in TNF-α, CXCL8, and CXCL1 would also be observed during selection of tumor cells for survival in increasing concentrations of docetaxel." (PMID 28915246, 2017). "Whether the MCTC mast cell phenotype infiltrates the tumour islets, expresses TNFα, and confers a survival advantage has not been reported." (PMID 27922077, 2016). "However, as the stimulus induced by CD28 tumor-targeting promotes Th1 cytokines (IFN-γ, TNF-α) but it also promotes the immunosuppressive cytokines (IL-10), we reasoned that, in order to have an antitumor effect, the immunosuppressive environment should be diminished." (PMID 26992239, 2016). "Overall, our data support the notion that MDSCs may be a target for anti-tumor therapy in patients and it also highlights TNF as a mediator with non-redundant pro-tumorigenic functions." (PMID 27148266, 2016). "This may explain the poor outcome of phase I clinical trials of VNP20009, which failed to induce sufficiently high TNF-alpha concentrations spikes in the human body, thus hampering Salmonella entry into tumor tissues." (PMID 27190519, 2016). "Indeed, MSC can interfere with the recognition of tumor cells by immune system producing and releasing immunoregulatory factors as TGFβ, prostaglandin E2 (PGE2), tumor necrosis factor α (TNFα), indolamine 2, 3-dioxygenase (IDO), hemeoxygenase (HO), NOS2, ARG1–2, IL10." (PMID 26967390, 2016). "However, based on the significant increase in infiltration of macrophages and NK cells into the tumor microenvironment in mice treated with Ad.EPCR, it is likely that macrophages and NK cells are the primary sources of the production of TNFα and IFNγ, respectively." (PMID 27833109, 2016).
tumor (continued). "In addition, mixed phenotypes of TAMs that co-express proinflammatory genes such as TNF and IL-1 together with known tumor-promoting genes including VEGFA and MMP9 have been observed in various tumor models including renal cell carcinoma and mammary adenocarcinoma." (PMID 27487154, 2016). "As such, rather than promoting tumor cell survival in the tumor microenvironment, TNF and LT-α may become cytotoxic in the presence of SMAC mimetics targeting cIAP1 and cIAP2." (PMID 27617834, 2016). "Furthermore, our results suggested that the cytokines IFN-γ and TNF-α play a critical role in MSC polarization, but other factors secreted by the TIL or tumor cells used in our model might have contributed to the observed MSC phenotypical changes." (PMID 27211104, 2016). "We next examined the cytokine profiles of tumor-infiltrating lymphocytes following ex vivo stimulation, and found that T cells in the CCR4 antagonist-treated group secreted significantly higher amounts of IFN-γ, IL-2, and TNF-α than T cells in the control groups (P < 0.05 for each)." (PMID 27177223, 2016). "However, following stimulation with α-c-myc tag monoclonal antibody or the tumor cells 24JKERB, we detected a range of cytokines, including IL-4, IL-2, IL-17A, TNF-α, IL-6 and IFN-γ from CAR T cells, while no significant response was observed from WT T cells." (PMID 27153556, 2016). "To understand roles of TNF-α in PDAC initiation, we sought to determine whether TNF-α expression level is aberrant in pancreatic intraepithelial neoplasia (PanIN) lesions, PDAC lesions, PDAC tumor cells, and PSCs cell lines." (PMID 27835602, 2016). "The production of TNFα by both mast cell phenotypes within the tumour islets, and the degranulation of the MCT phenotype within the tumour stroma, may be particularly important for their interaction with other immune cells and the associated inhibition of tumour progression." (PMID 27922077, 2016). "One extreme activation mode is the classically or M1-activated macrophages, which are activated to kill pathogens and tumor cells and accordingly express MHC class II and costimulatory molecules, Fc receptors to enhance phagocytosis, and proinflammatory and cytotoxic mediators (e.g., NO, TNFα)." (PMID 26997761, 2016). "Therefore, in the present study, overexpression of IFN-γ, TNF-α, and COX-2 mRNA might accelerate IDO induction and L-kynurenine elevation in hepatic tumors, which subsequently enhances tumor-induced immune tolerance in the livers of IDO-WT mice." (PMID 26727596, 2016). "Similarly, in a murine model of melanoma, T-cell cytokines IFN-γ and TNF-α synergized with vemurafenib, a BRAF oncogene inhibitor, to induce cell-cycle arrest of tumor cells in vitro, underscoring the importance of CD4+ T cell mediated immunity against cancer cells." (PMID 27766079, 2016). "However, very similar effects on tumor growth were observed for a different TNFR2 agonist mAb which does not compete with TNF-α, demonstrating that antagonism did not contribute appreciably to the therapeutic activity of the anti-TNFR2 mAbs." (PMID 27626702, 2016). "Why the TNFα-blocking antibody could not fully block NA-induced tumor cell death needs to be studied in the future." (PMID 25575821, 2015). "However, levels of IL-1α, IL-4, IL-10, IL-13, and TNFα were not significantly altered by tumor growth." (PMID 26347589, 2015). "PRKCDBP is a proapoptotic tumor suppressor which is activated by NF-κB in response to TNFα, suggesting that PRKCDBP inactivation may contribute to tumor progression by reducing cellular sensitivity to TNFα." (PMID 25986046, 2015). "By contrast, as IFN-γ-treated tumors contained high levels of endogenous cytokines TNF-α, IL-12p70 and IL-1β and the tumor-infiltrating macrophages did not express putative M2 marker CD206, we find it likely that IFN-γ instead skewed the macrophages towards M1 phenotype." (PMID 26107883, 2015).
tumor (continued). "Our results show that the serum levels of IL-6 were only slightly affected by tumor at day 28, while the serum levels of IFN-γ were not increased, and serum TNF-α was undetectable (data not shown) in 4T1 tumor-bearing mice up to day 28 after tumor cells implantation." (PMID 25822717, 2015). "Further analysis of excised intestinal polyps showed that the adoptive transfer of Apc HET Tregs reduced the levels of proinflammatory mediators IL-6, IL-1β, and IL-23 in the tumor microenvironment compared with wild type intestinal tissue but the expression level of TNF was not decreased." (PMID 26146642, 2015). "After TNF-α treatment, significantly smaller tumors were observed on the left side of the mice which was inoculated with FAT10 siRNA (FATi) expressing cells compared to the right flank which was injected with control siRNA (Ctrli) suggesting that the FAT10 gene augmented tumor growth." (PMID 26142316, 2015). "In addition, COX-2 is an early gene that is rapidly induced by pro-inflammatory cytokines (interleukin (IL) 1β, IL2 and tumor necrosis factor (TNF)), growth factors (EGF and platelet-derived growth factor (PDGF)), lipopolysaccharides, bile acids, ultraviolet B irradiation and tumor promoters." (PMID 25595899, 2015). "However, these authors did not evaluate the effects of solvent alone nor of TNF-α / LPS stimulation in tumor cell lines." (PMID 26511466, 2015). "Thus, we speculate that the ADT-induced production of CCL2 via TNF signaling is a feature of a population resembling PSA−/lo (progenitor) cells, and contributes to the aggressive tumor phenotype of this cancer population, which expands following ADT." (PMID 26327448, 2015). "While this assumption may not hold in all model systems, the presence of TNF α in the tumor was also dependent on CD8 + T cell activation." (PMID 26048402, 2015). "In addition, the release of danger signals or cytokines such as TNF-α and IFN-γ by radiation-damaged tumor cells promote DC maturation and cross-presentation resulting in the regression of more distant tumor masses through activation of tumor-specific T cells." (PMID 26500646, 2015). "In contrast, early effector cell-dependent infiltration within 20–30 min and restored anti-tumor reaction was observed by PP-treated NK cells against cetuximab-coated HNSCC clusters after 1 h (upper row) accompanied by raised IFN-γ and TNFα medium levels (24 h PP + 1 μg/ml Cetmab + 4 h HNSCC cells)." (PMID 26579120, 2015). "Thus, ELISAs were carried out to quantify the secreted levels of the proteins identified above and to investigate whether the tumour cells secreted other known pro-angiogenic factors including VEGF-A and TNF-α." (PMID 26407999, 2015). "TRAIL or tumor necrosis factor (TNF) related apoptosis-inducing ligand is a member of the TNF superfamily of proteins, whose best characterized function is the induction of apoptosis in tumor, infected, or transformed cells through activation of specific receptors." (PMID 25759846, 2015). "Hence, our data strongly suggests that in absence of TNF-α, tumor derived gangliosides interact directly with the TNFRI, to induce downstream signaling events leading to caspase activation and consequent apoptosis." (PMID 26226135, 2015). "In previous studies with anti-tumoral macrophages, NO, ROS or TNFα were shown to slow down tumor growth in vitro, which may reveal cytostatic rather than cytotoxic effects." (PMID 26337837, 2015). "Bayesian networks detected NF-κB dependency on NF in non-tumor MCF10A (genetic subtype Basal B, morphological group L/B), MCF7 (Luminal, L1), SUM159 (Basal B, L/B), and MDA-MB-231 (Basal B, B) cells, but not in HCC1954 (Basal A, L1) and AU565 (Luminal, L2) cells stimulated with TNFα (Fig2D)." (PMID 26148352, 2015).
tumor (continued). "It is possible that pre-treatment TNF-α level is related to tumor burden and that early treatment effect may begin to reduce this TNF-α input shortly upon treatment, which may explain the decline of TNF-α levels in the saline group with the highest baseline values." (PMID 25909710, 2015). "Treatment of MP2 with fixed NK cells treated with IL-2 + anti-CD16mAb + sAJ2 + anti-TNF-α had slight enhancing effect on tumor growth, whereas fixed NK cells obtained from anti-IFN-γ in combination with IL-2 + anti-CD16mAb + sAJ2-treated NK cells enhanced tumor cell growth substantially." (PMID 26697005, 2015). "IFN-γ, but not TNF-α, could significantly reduce the expression of Bv8 and Mmp9 in the neutrophils from tumor-bearing mice and pG/pI6-mice, and abrogate the promoting effect of T-sMs on the expression of Bv8 and Mmp9." (PMID 25587026, 2014). "In addition, tumor cells induce T and NK cell apoptosis, block lymphocyte homing and activation, and dampen macrophage and dendritic cell function by releasing immunosuppressive factors such as Fas, VEGF, IL-6, IL-10, TNF-α, GM-CSF, and IL-1β." (PMID 24995006, 2014). "The tumor necrosis factor (TNF)-related apoptosis-inducing ligand (TRAIL), a member of the tumor necrosis factor super-family, has attracted great interest for clinical applications due to its specific anti-tumor potential without toxic side effects to normal healthy cells." (PMID 25127663, 2014). "However, in this case, tumour development was preceded by skin inflammation and epidermal hyperplasia that depended on TNF signalling as the skin lesions did not develop when the mice were crossed into the TNFR1-deficient genetic background." (PMID 24952939, 2014). "Interestingly, q-PCR revealed that the expression levels of IL-1β, IL-6 and MIP-2 as well as IFN-γ and TNF (data not shown) in the colonic tissue, especially in the tumor area, were suppressed by the treatment with ML-7 as well as with MP6-XT22." (PMID 24520376, 2014). "Moreover, blocking of IL-1 receptor, combined blocking of TNF-α and IL-1 receptor, or inhibition of nitric oxide and reactive oxygen species did not significantly interfere with the inhibition of tumor cell growth by activated macrophages." (PMID 24612598, 2014). "Other proinflammatory factors found in tumors include TNF-α and IFN-γ (and our unpublished data), which may be TAM or T cell derived; they may occupy a niche in which tumor cells are being killed, or they may contribute to a chronically inflamed niche that is protumorigenic." (PMID 24955376, 2014). "Since expanded γδT cells retain the capacity to secrete pro-inflammatory cytokines (IFNγ, TNFα) and to express, albeit at reduced levels, lymph node-homing markers (CCR7, CD62L), the infusion of tumor-antigen-loaded γδT cells may be followed by a single treatment with zoledronate." (PMID 25101086, 2014). "Oral administration of DAEB can increase the relative spleen and thymus weight of tumor-bearing animals, promote secretion of tumor necrosis factor alpha (TNF-α), stimulate lymphocyte proliferation, and augment phagocytosis and secretion of NO and TNF-α in peritoneal macrophages." (PMID 25257786, 2014). "The expression levels of tumor promoting M2 markers: Cox 2, uPA, MMP9, MMR, arginase and VEGF are significantly higher in Mθs sorted from LLC tumors of WT while Mθs sorted from Rac2-/- mice displayed higher levels of proinflammatory cytokines, which are considered as M1 markers; IL1 and TNFα." (PMID 24770346, 2014). "Gemcitabine did not influence tumor mass iNOS and TNF-α immunoreactivities in this experiment." (PMID 25477992, 2014). "Although TNF-α could suppress tumor growth by directly inducing the apoptosis of tumor cells via TNFR-1, the neutrophils recruited to local tissue were important for the anti-tumor effect of TNF-α." (PMID 25587026, 2014).